SORBS2 (sorbin and SH3 domain containing 2)
Diseases named in the same sentence as SORBS2 in open-access papers (continued):
Sharing a sentence is not in itself a finding about the gene and the disease.
heart failure (4 papers, 2021 to 2025). Inability of the heart to pump blood at an adequate rate to meet tissue metabolic requirements. "Using mouse models and cardiac tissue from human heart failure patients, we demonstrated that SORBS2 expression is consistently increased during pathological remodelling, correlates to disease severity, and is regulated by GATA4." (PMID 39957251, 2025). "Previous research reported that myocardial Sorbs2 expression was consistently upregulated in humans with ischemic and idiopathic cardiomyopathies, as well as in experimental animal models of heart failure." (PMID 39502510, 2024). "As reported in previous studies, SORBS2 enhances the occurrence of LVNC by potentiating heart failure, but the specific mechanism remains unclear." (PMID 35050860, 2022). "Emerging evidence demonstrates that SORBS2 contributes to microtubule densification, also altering the distribution of JP2, leading to excitation-contraction (E-C) coupling, and may cause heart failure." (PMID 35050860, 2022). "SORBS2 has been reported to be upregulated in patients with left ventricular noncompaction cardiomyopathy and heart failure." (PMID 34558411, 2021).
cardiomyopathy (3 papers, 2020 to 2025). A disease of the heart muscle or myocardium proper. "DNAJB6 and SORBS2 were identified as new candidate cardiomyopathy susceptibility genes, which were supported by evidence from sequencing data from human patients." (PMID 33329049, 2020). "Interestingly, all three deleterious mutants identified from that approach, ANO5, DNAJB6(L), and SORBS2, were either causative or susceptibility genes for cardiomyopathies." (PMID 33329049, 2020). "Since SORBS2 is a structural component of sarcomeric Z-line and cardiomyopathy gene, we examined the myofibril structure of differentiated cardiomyocytes." (PMID 34099102, 2021).
clear cell renal cell carcinoma (3 papers, 2020 to 2024). "For example, SORBS2 inhibited renal clear cell carcinoma metastasis by enhancing MTUS1 mRNA stability; RBM38 increased PREN stability and enhanced its expression to promote breast cancer progression progress." (PMID 36463205, 2022).
Obesity (3 papers, 2020 to 2022). Accumulation of substantial excess body fat. "The DMR showing the strongest association was annotated to SORBS2, which has previously been described as an overlapping gene between mood disorders and obesity." (PMID 35794104, 2022). "However, we cannot exclude that further confounding lifestyle factors might have influenced our results, e.g., methylation in SORBS2 has been linked to obesity." (PMID 35794104, 2022). "We suggest that SORBS2 is related to obesity through the innate immunity and inflammation response by the Notch signaling pathway that plays a major role in adipogenic differentiation." (PMID 32942585, 2020). "Pathway analysis interaction for TAPBP, BDNF, and SORBS2 confirmed the relation of these genes in both obesity and mood disorders." (PMID 32942585, 2020). "SORBS2: The role of SORBS2 gene in obesity and mood disorders has been discovered recently by different genome-wide methylation studies." (PMID 32942585, 2020). "This included the SORBS2 locus manifesting higher methylation and lower expression in OVAT of subjects with obesity, in agreement with our results showing a significantly lower methylation in responders compared to non-responders (data not shown)." (PMID 33198820, 2020).
ovarian tumors (3 papers, 2018 to 2022). "When they utilized a knockdown murine model for SORBS2, they observed increased metastatic behaviors of the ovarian tumors, and noted increased MDSC levels and M2 (suppressive) polarization of TAMs." (PMID 31354741, 2019). "Subsequently, they reported decreased survival among the mice with SORBS2 knockdown, thus concluding that SORBS2 plays a role in suppressing the invasion of ovarian tumors." (PMID 31354741, 2019). "We observed in the CSIOVDB database that there was significant reduction of SORBS2 expression in ovarian tumors compared with normal ovarian surface epithelium." (PMID 29548303, 2018). "Moreover, we analyzed the differential expression of SORBS2 in (a) BRCA1 mutant and BRCA2 mutant tumor tissues compared with wild-type tumor tissues; (b) CCNE1high and CCNE1low ovarian tumor tissues in TCGA dataset." (PMID 29548303, 2018).
Alzheimer disease (2 papers, 2018 to 2025). A progressive, neurodegenerative disease characterized by loss of function and death of nerve cells in several areas of the brain leading to loss of cognitive function such as memory and language. "This SNP locates at the intergenic region between SORBS2 and TLR3 at Chromosome 4 and are 72k downstream of SNP rs75718659, which was reported associated with Alzheimer’s disease in a family-based GWAS." (PMID 30133451, 2018).
arrhythmogenic right ventricular cardiomyopathy (2 papers, 2021 to 2023). "Loss of the SORBS2 protein in mouse results in phenotypes characteristic of human arrhythmogenic right ventricular cardiomyopathy (ARVC), including dilated right ventricle (RV), RV dysfunction, spontaneous ventricular tachycardia (VT), and premature death." (PMID 34473707, 2021). "Interestingly, Sorbs2 encodes an intercalated disc (ICD) protein and homozygous Sorb2 KO mutant manifests arrhythmogenic right ventricular cardiomyopathy (ARVC)-like phenotypes, including enlarged right ventricle and cardiac arrhythmia." (PMID 36970353, 2023).
atrial septal defect (2 papers, 2021 to 2024). Interauricular communication is a congenital malformation characterized by a communication between the atrial chambers of the heart. "Previously, we reported that the structural protein Sorbs2 promotes the development of the second heart field, with its deficiency resulting in atrial septal defects (ASD)." (PMID 39882075, 2024). "However, we found that about 40% (12/30) Sorbs2-/- hearts had atrial septal defect (ASD) with 10 being the absence/hypoplaisa of primary septum and two being double atrial septum (DAS)." (PMID 34099102, 2021).
cervical carcinoma (2 papers, 2013 to 2021). A carcinoma arising from either the exocervical squamous epithelium or the endocervical glandular epithelium. "Among the 6 most likely target genes, hsa-miR-484 may involve in the development of cervical lesion by targeting SORBS2, a tumor suppressor in cervical cancer." (PMID 34335927, 2021). "The effect of ectopic expression of SORBS2, TLR3, CYP4V2, FBXO18, IL15RA, WDR37 and DIP2C on the cell phenotype, in particular senescence, was investigated in primary cells, HPV-immortalized cells and cervical carcinoma cells." (PMID 24165198, 2013).
glioma (2 papers, 2024 to 2025). A benign or malignant brain and spinal cord tumor that arises from glial cells (astrocytes, oligodendrocytes, ependymal cells). "High levels of SORBS2 protein in glioma cells may stabilize mRNAs associated with tumor suppression and increase glioma cell TMZ sensitivity." (PMID 38177123, 2024). "By contrast, the SORBS2 locus, which encodes a gene downregulated in LINC02454 KD glioma cells, showed significant interaction with the LINC02454 enhancer based on Capture-C data." (PMID 38177123, 2024). "Our findings suggest that SE activity at the LINC02454 locus increases glioma cell sensitivity to TMZ by regulating expression of SORBS2 (Sorbin and SH3 domain containing 2) via long-range chromatin interactions, and that LINC02454 maintains this chromatin loop." (PMID 38177123, 2024). "In conclusion, our study shows that LINC02454 increases glioma cell TMZ sensitivity by maintaining chromatin interactions between the SORBS2 gene and a LINC02454 enhancer and at the same time can decrease TMZ sensitivity of glioma cells by promoting DDR1 expression." (PMID 38177123, 2024). "On one hand, LINC02454 maintains a long-range enhancer–promoter loop that upregulates SORBS2, a gene whose expression was found to increase TMZ sensitivity in glioma cells." (PMID 41154382, 2025). "An important finding reported here is that SORBS2 and DDR1 are two major genes regulated by LINC02454, and that both regulate glioma cell sensitivity to TMZ." (PMID 38177123, 2024). "To verify SORBS2 function in regulating glioma cell sensitivity to TMZ, we performed SORBS2 OE followed by qRT-PCR analysis and confirmed a 170-fold upregulation in SORBS2 transcript levels in glioma cells." (PMID 38177123, 2024). "Compared with TMZ (1 mM)-treated control glioma cells, we observed significantly increased LDH release in similarly treated SORBS2 OE cells." (PMID 38177123, 2024). "On one hand, LINC02454 activity enhanced SORBS2 expression by maintaining 3D chromatin interactions via the LINC02454 SE, increasing glioma cell sensitivity to TMZ." (PMID 38177123, 2024). "Analysis of gene expression data from TCGA and GTEx databases showed significant downregulation of SORBS2 transcripts in GBM and low grade glioma (LGG) relative to normal control samples, suggesting that SORBS2 functions as a tumor suppressor in this context, an activity reported by others." (PMID 38177123, 2024). "Our findings also indicate that SORBS2 and DDR1 could be therapeutic targets to enhance glioma cell TMZ sensitivity." (PMID 38177123, 2024).
mood disorder (2 papers, 2020 to 2022). A cognitive disorder a disturbance in which the person's mood is hypothesized to be the main underlying feature. "SORBS2 may therefore be a potential target gene enabling better understanding of mood disorders and additionally antidepressant treatment response, but confirmation in larger samples is needed." (PMID 35794104, 2022). "Additionally, to the grapevine, SORBS2 is related to mood disorders through two different pathways; actin-related proteins and the Notch signaling pathway." (PMID 32942585, 2020).
osteosarcoma (2 papers, 2021 to 2024). A usually aggressive malignant bone-forming mesenchymal neoplasm, predominantly affecting adolescents and young adults. "Again, we identified nine genes related to differences in immune cell infiltration in osteosarcoma, four of which are SORBS2, BAIAP2L2, SNAPC3 and ZDHHC21 with low abundances and they have higher disease-free survival probability than the group with high abundances." (PMID 34922489, 2021).
acute myocardial infarction (1 paper, 2014). Necrosis of the myocardium, as a result of interruption of the blood supply to the area. "From a mass spectrometry based proteomics approach, SORBS2 has been recently identified as a protein released from cardiac tissue immediately following acute myocardial infarction." (PMID 25117565, 2014).
atherosclerosis (1 paper, 2022). A disease characterized by the build-up of fatty material and calcium deposition in the arterial wall resulting in partial or complete occlusion of the arterial lumen. "Our study may be a useful complement to prescription of patients with FH, since inhibition of SORBS2 could block the inflammation process thus reducing atherosclerosis." (PMID 35590369, 2022). "Our studies reveal that SORBS2 silencing inhibited activation of the NLRP3/ caspase-1/ IL-1β pathway, ultimately blocking the inflammation process in AS, and thus potentially providing protection against hypercholesterolemia and atherosclerosis." (PMID 35590369, 2022).
Cognitive impairment (1 paper, 2025). Abnormal cognition is characterized by deficits in thinking, reasoning, or remembering. "Our findings demonstrate that overexpression of the SORBS2 T189M variant in a murine model induces neuroinflammation, exacerbates Aβ pathology, accelerates neurodegeneration, and culminates in cognitive impairment." (PMID 39912518, 2025). "Overexpression of SORBS2 T189M variant in a murine model activated microglia, up‐regulated inflammatory cytokines, induced neuroinflammation, exacerbated Aβ accumulation, accelerated neurodegeneration, and ultimately led to cognitive impairment." (PMID 39912518, 2025).
colon cancer (1 paper, 2023). "Sorbin and SH3 domain containing 2 (SORBS2) promotes colon cancer migration though activation of the Notch pathway." (PMID 38033043, 2023).
coronary heart disease (1 paper, 2022). "Of the top 20 upregulated genes, SORBS2 was found to be associated with coronary artery disease, and was chosen as a gene of interest for further study." (PMID 35590369, 2022). "Sorbin and SH3 Domain Containing 2 (SORBS2) is known to play a role in coronary heart disease (CHD)." (PMID 35590369, 2022).
diabetic cardiomyopathy (1 paper, 2020). Diabetic cardiomyopathy is a disorder of the heart muscle in people with diabetes. "Proteomics analysis presented that SORBS2 was obviously upregulated in the diabetic cardiomyopathy model." (PMID 32905431, 2020).
dilated cardiomyopathy (1 paper, 2024). Cardiomyopathy which is characterized by dilation and contractile dysfunction of the left and right ventricles. "Dysregulation of SORBS2 (Sorbin and SH3 domain containing 2), an adaptor protein that facilitates protein-protein interactions among many cytoskeletal and membrane-associated proteins, has been implicated in dilated cardiomyopathy and arrhythmogenic cardiomyopathy." (PMID 39803589, 2024).
facioscapulohumeral muscular dystrophy (1 paper, 2020). An autosomal dominant disorder affecting the skeletal muscles of the face, scapula, and upper arm. "In the age-associated genetic disease facioscapulohumeral muscular dystrophy SORBS2 transcription is altered by a telomeric 4.8-Mb loop in patients ́ myoblasts." (PMID 32564008, 2020).
folate deficiency (1 paper, 2019). A nutritional condition produced by a deficiency of FOLIC ACID in the diet. "Thirdly, genes with an opposite expression pattern in folate deficiency and repletion cell lines: SORBS2, DCN, SLFN11, RUNX3, GALC, and HSPB7." (PMID 30836646, 2019).
frontotemporal dementia (1 paper, 2025). Frontotemporal dementia (FTD) comprises a group of neurodegenerative disorders, characterized by progressive changes in behavior, executive dysfunction and language impairment, as a result of degeneration of the medial prefrontal and frontoinsular cortices. "Located in exon 9 of SORBS2, this variant has not been previously reported in AD or frontotemporal dementia (FTD) mutation databases." (PMID 39912518, 2025).
Hypercholesterolemia (1 paper, 2022). An increased concentration of cholesterol in the blood. "However, the role of SORBS2 in hypercholesterolemia and its underlying molecular mechanisms remain poorly understood." (PMID 35590369, 2022). "However, the mechanism underlying SORBS2 involvement in the development of hypercholesterolemia remains unknown." (PMID 35590369, 2022). "SORBS2 regulates lipid-induced inflammation and foam cell formation, and is a potential therapeutic target for hypercholesterolemia." (PMID 35590369, 2022). "Hence, SORBS2 silencing could act as a natural antioxidants for patients with familial hypercholesterolemia.Our findings reveal that SORBS2 silencing inhibited OxLDL-induced ROS production." (PMID 35590369, 2022).
orofacial cleft (1 paper, 2013). A disorder of facial skeleton that is characterized by cleft lip and/or cleft palate that result in feeding, speech and hearing problems caused by failures during development. "The author suggested that the critical region for the syndrome resides in 4q35.1, implicating gene SORBS2 for orofacial clefts and congenital heart defects." (PMID 24176130, 2013).
preeclampsia (1 paper, 2025). Preeclampsia is a hypertensive disorder of pregnancy that is characterized by new-onset hypertension with proteinuria presenting after 20 weeks of gestation, and depending on mild or severe forms may initially present with severe headache, visual disturbances, and hyperreflexia. "A recent study linked preeclampsia with decreased expression of the RNA-binding protein SORBS2, which promotes glycolysis, cell proliferation, and migration of HTR-8/SVneo cells by increasing the stability of the HK2 enzyme (Song L 2024)." (PMID 40251569, 2025).
Stroke (1 paper, 2020). Sudden impairment of blood flow to a part of the brain due to occlusion or rupture of an artery to the brain. "Sspo, Shroom3, MuSK, Chrna2, Sorbs2, and Coro6 were upregulated in response to stroke." (PMID 32629989, 2020).
type II diabetes (1 paper, 2022). "Genetic variation in SORBS2 has previously been implicated in cardiovascular diseases, type II diabetes, and educational attainment in European ancestry populations." (PMID 35794104, 2022). "Twenty DMRs were associated with response; the strongest in an enhancer region in SORBS2, which has been related to cardiovascular diseases and type II diabetes." (PMID 35794104, 2022).